CEP290 (centrosomal protein 290)
Diseases named in the same sentence as CEP290 in open-access papers (continued):
Sharing a sentence is not in itself a finding about the gene and the disease.
Bardet-Biedl syndrome (26 papers, 2010 to 2025). A ciliopathy with multisystem involvement. "ARL6 and CEP290 are 2 of the most frequently mutated genes in Bardet-Biedl syndrome, a multisystem primary ciliopathy characterized by heterogenous clinical manifestations, including cognitive impairment and developmental delay." (PMID 40924492, 2025). "CEP290 (Centrosomal Protein 290): Bardet-Biedl syndrome 14 (vision loss, obesity, type 2 diabetes, hypercholesterolemia, polydactily, intellectual disability, impaired speech, delayed psychomotor development, and behavioral alterations)." (PMID 31031802, 2019). "Of note, the CEP290 gene is also responsible for non-syndromic forms of LCA (specifically LCA10) and some cases of Bardet–Biedl syndrome (BBS14)." (PMID 39940729, 2025). "Its many names can be attributed to the diverse spectrum of clinical manifestations, including Bardet-Biedl syndrome (BBS), nephronophthisis, Joubert syndrome, Senior-Loken syndrome, Meckel-Gruber syndrome, and Leber congenital amaurosis, associated with mutations in the Cep290 gene." (PMID 24053599, 2013). "For example, Centrosomal protein of 290 kDa (CEP290, also known as NPHP6), which represents the most common cause of LCA identified to date, is also associated with other diseases, such as retinitis pigmentosa, Meckel syndrome (MKS), SLSN, Bardet-Biedl syndrome (BBS) and JBTS." (PMID 22219648, 2011).
retinal disease (17 papers, 2012 to 2024). "Leber congenital amaurosis type 10 (LCA10) is a severe retinal disease caused by biallelic variants in the ciliary gene CEP290." (PMID 37371046, 2023). "Diagnostic genetic testing via whole genome sequencing and virtual inherited retinal disease gene panel evaluation finally identified two compound heterozygous variants c.4452_4455del;p.(Lys1484Asnfs*4) and c.2414T > C;p.(Leu805Pro) in the CEP290 gene." (PMID 37642804, 2023). "CEP290-associated Leber congenital amaurosis type 10 (LCA10) is a retinal disease resulting in childhood blindness." (PMID 35379979, 2022). "RPGR complexes with other IRD proteins at the cilium, including CEP290, which is required for ciliogenesis and normal cilia trafficking, and pathogenic variants in this gene also cause a range of syndromic retinal diseases." (PMID 35330501, 2022). "The proof-of-principle for targeting splicing as potential therapeutic strategy is further supported by the application of antisense oligonucleotides for the treatment of inherited retinal diseases, including CEP290 associated LCA." (PMID 31344897, 2019). "The Rpgr-cko and Nrlko/ko/Cep290rd16/rd16 double mutants display appropriate characteristics for designing treatments of retinal disease caused by RPGR and CEP290 mutations." (PMID 23351659, 2012). "Indeed, the first FDA-approved clinical trial for in-body CRISPR gene therapy was a treatment for inherited retinal disease by using AAV-derived vectors to target the deep-intronic c2991 + 1655A > G single nucleotide mutation in the CEP290 gene." (PMID 36145593, 2022). "Moreover, mechanisms like basal exon skipping or nonsense-associated altered splicing as described for another retinal disease gene, namely CEP290, may well explain these apparent contradictory findings." (PMID 33467000, 2021). "These non-genetic influences, combined with the unique structural and functional demands of retinal cilia, highlight the complexity of CEP290-related retinal diseases." (PMID 39766851, 2024). "This was evident by the approval of the first CRISPR in vivo genome engineering clinical trial for inherited retinal disease by editing the CEP290 gene in Leber congenital amaurosis." (PMID 36145593, 2022). "For inherited retinal diseases, the first clinical trial based on AONs to redirect a splicing defect in CEP290 has recently shown promising results, whereas a second one, for USH2A, is currently ongoing (ClinicalTrials.gov: NCT03780257)." (PMID 32653833, 2020).
Leber congenital amaurosis 10 (15 papers, 2021 to 2026). Any Leber congenital amaurosis in which the cause of the disease is a mutation in the CEP290 gene. "For instance, a Phase 1/2 clinical trial (BRILLIANCE) is evaluating the safety and efficacy of EDIT-101, a CRISPR/Cas9-based therapy targeting the CEP290 mutation associated with Leber Congenital Amaurosis 10 (LCA10)." (PMID 40731809, 2025). "However, this approach was used in experiments in cell lines in vitro, as well as in humanized centrosomal protein 290 (CEP290) mice in vivo carrying the mutation in the CEP290 gene, responsible for Leber congenital amaurosis type 10." (PMID 37275547, 2023). "For example, targeted genomic deletion using CRISPR-Cas9 represents a promising a therapeutic approach for the treatment of Leber Congenital Amaurosis 10 (LCA10), a severe retinal dystrophy, in patients with an intronic mutation in CEP290." (PMID 33513969, 2021). "In light of these findings, a phase I/II clinical trial is underway to demonstrate the safety and efficacy of CRISPR/Cas9 gene therapy via subretinal delivery in patients with Leber Congenital Amaurosis Type 10 (LCA10), which is caused by the IVS26 mutation in the CEP290 gene (NCT03872479)." (PMID 38391665, 2024).
Meckel-Gruber syndrome (15 papers, 2010 to 2025). "However, we also observed a trend where genes that cluster in the same ciliary compartment tended to cause a similar phenotype; e.g., mutations in the transition zone genes CC2D2A, TCTN2, TMEM237, and CEP290 almost always resulted in either Joubert or Meckel-Gruber syndrome phenotypes." (PMID 27894351, 2016).
nephronophthisis (12 papers, 2009 to 2026). Progressive tubulointerstitial injury, inherited in an autosomal recessive pattern, caused by mutations in genes involved in ciliary function, which may result in an end stage renal failure. "It remains unclear how patients with JSRD having CEP290 gene mutations lead to kidney disorders, particularly polycystic kidney disease including nephronophthisis (NPH)." (PMID 40570958, 2025). "In patients with syndromic nephronophthisis caused by several genes (including NPHP3, IQCB1, CEP290, and MKS1), an additional heterozygous variant in RPGRIP1L is associated with retinitis pigmentosa." (PMID 37628633, 2023). "Common variants are associated with elevated creatine in association studies;In patients with syndromic nephronophthisis caused by several genes (including NPHP3, IQCB1, CEP290, and MKS1), an additional heterozygous variant in RPGRIP1L is associated with retinitis pigmentosa." (PMID 37628633, 2023). "NPHP6/CEP290 gene is one of the most common causes of isolated LCA overall, without nephronophthisis." (PMID 38522724, 2024).
Senior-Loken syndrome (12 papers, 2011 to 2023). Senior-Loken syndrome (SLSN) is a very rare autosomal recessive oculo-renal disease characterized by the association of nephronophthisis (NPHP), a chronic kidney disease, with retinal dystrophy. "NPHP5/IQCB1 is a causal gene of LCA and Senior-Löken syndrome (SLS), and LCA and SLS patients with NPHP5 mutations phenocopy CEP290-LCA and CEP290-SLS cases." (PMID 34520396, 2021).
Blindness (11 papers, 2016 to 2025). Blindness is the condition of lacking visual perception defined as a profound reduction in visual perception. "In this study, we have shown that spliceosome-mediated pre-mRNA trans-splicing can be utilized to edit transcripts of CEP290, which causes severe early-onset blindness (LCA10), which can also be accompanied by systemic disease." (PMID 30195768, 2018). "Reduction of CEP290 expression leads to several human diseases including a blindness condition termed Leber’s Congenital Amaurosis Type 10 (LCA10)." (PMID 29562890, 2018). "Mutations on the gene CEP290 (CEP290, OMIM #610142: autosomal recessive) cause CEP290-associated LCA characterized by the early and severe dysfunction of cone photoreceptors, and are the gene defects that represent the majority of LCA cases with severe blindness." (PMID 38610844, 2024). "Mutations in the gene for Centrosomal Protein 290 (CEP290) cause JBTS, MKS, BBS, and NPHP, but also account for 15–25% of cases of isolated blindness in LCA with no associated systemic disease." (PMID 30970040, 2019).
cone-rod dystrophy (6 papers, 2013 to 2025). Inherited retinal dystrophies that belong to the group of pigmentary retinopathies. "The other IRD group included Stargardt's disease carrying ABCA4 variants, as well as individuals with Cone-Rod Dystrophy (CORD) or RP presenting with various genetic variants such as RDH12, RPGR, LCA5,CEP290, RP2, USH2A, and EYS." (PMID 38466290, 2024). "Until now, four LCA genes account for congenital cone-rod dystrophy (LCA type I): GUCY2D, RPGRIP1, CEP290 and RD3 [present study]." (PMID 23308101, 2013).
Renal cyst (6 papers, 2006 to 2025). A fluid filled sac in the kidney. "With the cautions of the interpretation of hURECs and the use of cilia length as a biomarker of cystic kidney disease noted, our data suggests that CEP290 defects in renal tubular epithelium may be responsive to drug treatments." (PMID 28973549, 2017). "CEP290 or NPHP6 encodes for nephrocystin-6, a centrosomal protein that modulates the activity of ATF4, a transcription factor implicated in the cAMP-dependent renal cyst formation." (PMID 17112370, 2006).
retinal ciliopathies (6 papers, 2014 to 2024). "There are now several more genes being targeted for gene therapy in retinal ciliopathies including CEP290 (mutations in which cause LCA10); and LCA5." (PMID 30915099, 2019). "The phenotype of the cep290 and bbs2 zebrafish models of retinal ciliopathies is characterized by the degeneration of photoreceptors, chronic inflammation, and increased proliferation of rod precursor cells." (PMID 37293546, 2023). "George Witman and colleagues showed that CEP290/NPHP6, which is mutated in human retinal ciliopathies localizes to the Y-links of Chlamydomonas flagella." (PMID 26501325, 2015). "This review will discuss the state of hiPSC-derived retinal organoid technology for accurately modelling prominent retinal ciliopathies related to genes, including RPGR, CEP290, MYO7A, and USH2A." (PMID 38474133, 2024).
Obesity (5 papers, 2019 to 2025). Accumulation of substantial excess body fat. "Heterozygous carriage of recessive mutations was observed in the ADCY3 (adenylate cyclase 3), CEP290 (centrosomal protein), and TUB (Tubby-like protein) genes, which are involved in obesity pathogenesis." (PMID 40149731, 2025). "Additional cilia genes that are associated with obesity include CEP19, CEP290, MC4R, ADCY 3, and RPGRIP1L." (PMID 36568981, 2022).
congenital blindness (4 papers, 2019 to 2024). "Moreover, treatment of the CEP290 c.2991+1655A>G variant with the RNA antisense oligonucleotide (AON) sepofarsen (QR-110) restored CEP290 function in preclinical models, improved visual acuity in phase Ib/II clinical trials, and improved cone sensitivity in individuals with congenital blindness." (PMID 37371046, 2023).
Hydrocephalus (4 papers, 2012 to 2023). Hydrocephalus is an active distension of the ventricular system of the brain resulting from inadequate passage of CSF from its point of production within the cerebral ventricles to its point of absorption into the systemic circulation. "Surprisingly, all three mouse knockouts of Cep290 are viable as homozygotes, with a percentage dying due to hydrocephalus after birth." (PMID 36533556, 2022). "The zebrafish cep290 mutant has a partial penetrance phenotype conceptually like the mouse's partial penetrant hydrocephalus-derived lethality and the variability in human patient phenotypes." (PMID 36533556, 2022). "In humans with JSRD, hydrocephalus is a rarer finding, however recently mutations in the CC2D2A gene (whose protein product interacts with CEP290) have been associated with ventriculomegaly and hydrocephalus." (PMID 23028714, 2012). "For example, defaults in centrosomal protein Cep290 or intraflagellar transport (IFT) components such as Kinesin family member 3a (Kif3a), Ift188 and Ttc21b, impair primary cilia formation/signaling in turn disrupting ependymal cilia and leading to hydrocephalus in mice." (PMID 36859317, 2023). "To date, murine models of Ahi1 and Cep290 knockdown have not demonstrated gross hydrocephalus." (PMID 23028714, 2012).
Kidney Cyst (4 papers, 2009 to 2025). Abnormal fluid filled sac within the kidney, either acquired or congenital. "Development of kidney cysts in Cep290 knockout mice is progressive and cysts become more prominent at 2 weeks of age." (PMID 40247090, 2025). "In zebrafish, morpholino suppression of cep290 resulted in a genetic interaction with cc2d2a and synergistically enhanced kidney cyst phenotypes." (PMID 30970040, 2019). "Missense alleles of AHI1 were associated with increased neurological involvement in a small number of CEP290-LCA patients, while morpholino knockdown of cep290 increased the frequency of kidney cysts in cc2d2a-/- mutant zebrafish." (PMID 30970040, 2019). "Maternal zygotic (MZ) cep290fb208/fb208 mutants (hereafter referred to as MZcep290−/−) did not exhibit kidney cysts, otolith or left-right asymmetry defects, in accordance with previous reports from the zebrafish cep290 fh297 line." (PMID 34155518, 2021).
scoliosis (4 papers, 2019 to 2024). A congenital or acquired spinal deformity characterized by lateral curvature of the spine. "Mutation of the cep290 gene encoding another transition zone protein also associated astrogliosis with scoliosis." (PMID 39388365, 2024). "Indeed, Cep290 is markedly decreased in mak mutants, so it is possible that scoliosis and smaller body size in mak mutants are caused by reduced activity of Cep290 and Tmem216, respectively." (PMID 38813692, 2024). "Finally, we showed that another TZ gene mutant, cep290, also displayed astrogliosis at the time of scoliosis onset." (PMID 39388365, 2024). "Finally, we show that astrogliosis is conserved in another zebrafish ciliary TZ mutant, cep290, identifying a novel mechanism involved in scoliosis upon ciliary dysfunction." (PMID 39388365, 2024). "Finally, our observation of widespread astrogliosis in two TZ gene mutants, rpgrip1l and cep290, suggests that it could represent a general mechanism involved in scoliosis downstream of cilia dysfunction." (PMID 39388365, 2024).
Stargardt disease (4 papers, 2017 to 2025). "This is reasonable when we correlate the clinical phenotypes; CEP290 is related to LCA, RP1L1 is related to occult macular dystrophy (OMD), ABCA4 is related to Stargardt disease and severe forms of autosomal recessive RP, and CYP4V2 is related to BCD." (PMID 33608557, 2021).
Usher syndrome (4 papers, 2017 to 2025). A syndromic diseae characterized by the association of sensorineural deafness (usually congenital) with retinitis pigmentosa and progressive vision loss. "Targeting specific mutations in genes like USH2A (Usher Syndrome) or CEP290." (PMID 39439625, 2024). "As a result, expanded capacity vectors can now accommodate genes such as CEP290, ABCA4, and MYO7A, genes responsible for LCA, SMD, and Type 1 Usher syndrome, respectively." (PMID 29326851, 2017). "Nonviral vectors developed through studies on vector capacity have increased the number of target genes, and genes such as CEP290 in LCA, ABCA4 in SMD, and MYO7A in Type 1 Usher syndrome are currently within capacity." (PMID 29326851, 2017).
achromatopsia (3 papers, 2017 to 2024). Achromatopsia (ACHM) is a rare autosomal recessive retinal disorder characterized by color blindness, nystagmus, photophobia, and severely reduced visual acuity due to the absence or impairment of cone function. "In this report, we present a patient with cone-dominated IRD carrying biallelic heterozygous variants in CEP290, showing characteristics of achromatopsia, thereby broadening the spectrum of CEP290-associated disease." (PMID 37642804, 2023). "Here, we present an unusual non-syndromic case of a juvenile retinal dystrophy caused by biallelic CEP290 mutations imitating initially the phenotype of achromatopsia or slowly progressing cone dystrophy." (PMID 37642804, 2023). "Additionally, the identified CEP290 mutations were analyzed in persons with achromatopsia (ACHM) (n = 23) and autosomal recessive or isolated cone dystrophy (CD; n = 145)." (PMID 28829391, 2017). "Stationary IRDs constituted 14.2% (3.1% albinism, 4.7% CSNB, 5.4% achromatopsia), variants causative for LCA were assigned to 8.5% (CEP290, GUCY2D, RDH12, CREB1, RPE65, RD3), 6% were annotated in RS1, and 3.1% were annotated in CHM." (PMID 39596324, 2024).
Anosmia (3 papers, 2011 to 2022). An inability to perceive odors. "In patients with CEP290-LCA, the presence of residual CEP290 protein is proposed to be associated with a relatively milder phenotype, limited to vision loss and anosmia, in contrast to more severe pleiotropic phenotypes observed with other CEP290 mutations." (PMID 36084637, 2022).
brain malformations (3 papers, 2022 to 2025). "This includes severe brain malformations, mental retardation, seizures, psychomotor developmental delay, and cardiac, urinary, and gastrointestinal abnormalities (the associated genes are: DNML, CEP290, CASK, PIGN)." (PMID 36421828, 2022).
breast carcinoma (3 papers, 2020 to 2023). "Interestingly, we observed significantly elevated levels of PCM1 and CEP290, but not others in DNAJA2-deficient mouse breast cancer cell line 4T1 and HeLa cells." (PMID 37640708, 2023).
myopia (3 papers, 2018 to 2025). "The rarer, cone-dominated CEP290-associated dystrophy has been found to present with myopia." (PMID 40535564, 2025). "Thus, our observation that early-onset cone degeneration is associated with high myopia is also seen in CEP290; another ciliary protein which shares a similar structural and functional role with RPGR." (PMID 40535564, 2025). "In addition to the novel mutations found in five known myopia genes (ADAMTS18, CSMD1, P3H2, RPGR, and SLC39A5), we also identified pathogenic variants in seven ocular disease genes (ABCA4, CEP290, HSPG2, PCDH15, SAG, SEMA4A, and USH2A) as novel candidate genes." (PMID 30245926, 2018).
polycystic kidney (3 papers, 2020 to 2025). "The expression of ARL13B in foetal polycystic kidney tissues with mutated CEP290 protein was similar to the normal kidney tissues with wild‐type CEP290 protein." (PMID 31840411, 2020). "Immunofluorescence study showed that the expression of mutated CEP290 was quite lower in foetal polycystic kidney tissue in comparison with the expression of wild‐type CEP290 protein in normal kidney tissue, which was consistent with the results of Western blot." (PMID 31840411, 2020). "In order to observe the effect of CEP290 variant on ciliary structure, we detected the localization and expression of ARL13B (ADP‐ribosylation factor‐like protein 13B) in both normal and foetal polycystic kidney tissues by immunofluorescence assay." (PMID 31840411, 2020). "Additionally, we also observed that the wild‐type CEP290 protein is localized into the ciliary base in normal kidney tissue while we found no expression of mutated CEP290 protein in foetal polycystic kidney tissue." (PMID 31840411, 2020).
renal failure (3 papers, 2024 to 2026). "The renal disease associated with CEP290 mutations is mainly characterized by juvenile NPHC, with the onset of renal failure typically occurring during the first or second decade of life." (PMID 38671609, 2024).
autism (2 papers, 2018 to 2019). Persistent deficits in social interaction and communication and interaction as well as a markedly restricted repertoire of activity and interest as well as repetitive patterns of behavior. "The present study shows that the mouse analogue of the autism-associated R1746Q mutation in CEP290 has a dominant negative effect on the regulatory function of CEP290 to coordinate cell proliferation and to stabilise the molecular integrity of the primary cilium." (PMID 30478281, 2018).